MALAT1 (metastasis associated lung adenocarcinoma transcript 1)
Diseases named in the same sentence as MALAT1 in open-access papers (continued):
Sharing a sentence is not in itself a finding about the gene and the disease.
breast cancer (continued). "In addition, MALAT1 reversed the inhibitory effect of miR-124 on breast cancer proliferation and was involved in the cyclin-dependent kinase 4 (CDK4) expression." (PMID 26918449, 2016). "MALAT1 expression is deregulated in various tumors, including breast cancer." (PMID 27250026, 2016). "The prognostic value of MALAT1 in breast cancer was controversial in our study." (PMID 27191888, 2016). "We further investigated whether MALAT1 increased breast cancer cell proliferation and the cell cycle by targeting CDK4." (PMID 26918449, 2016). "Few studies concerning MALAT1 in breast cancer are available." (PMID 27172249, 2016). "Recent studies have demonstrated that lncRNAs are involved in the development of different types of cancer, for example, metastasis associated lung adenocarcinoma transcript 1 (MALAT-1) in non small cell lung cancer and HOTAIR in breast cancer and colorectal cancer." (PMID 27751178, 2016). "ER's target genes, PGR and CCND1 were also overexpressed in MALAT1 altered group, indicating MALAT1 might play a role the regulation of ER expression in breast cancer." (PMID 27191888, 2016). "Thus, our findings provided new insights into the mechanism of breast cancer cell proliferation modulated by MALAT1-miR-124 -CDK4/E2F1 signaling pathway in the development of breast cancer." (PMID 26918449, 2016). "In TNBC and HER2+ breast cancer, MALAT-1 expression could be used as a potential prognostic marker, but not in luminal patients." (PMID 27608009, 2016). "Taken together, our data highlight the pivotal role of MALAT1 in breast cancer tumorigenesis." (PMID 26918449, 2016). "Expression profiles for MALAT1 were examined in 12 breast cancer cell lines." (PMID 27191888, 2016). "Our findings are of particular clinical significance as MALAT1 levels in breast cancer samples could be used to predict future onset of metastatic disease in LN- patients who might otherwise be perceived to be at a low risk for metastasis." (PMID 27250026, 2016). "To determine whether MALAT1 expression in breast cancer is capable of exerting prognostically significant effects, we compared DSS (disease-specific survival) between patients grouped according to high or low MALT1 expression." (PMID 27250026, 2016). "We also found that MALAT1 was increased in most breast cancer cells." (PMID 26918449, 2016). "A better understanding of MALAT1 function in different subtypes could be obtained by manipulating the levels of MALAT1 in breast cancer cell lines of various subtypes." (PMID 27250026, 2016). "Herein, we showed that MALAT1 was aberrantly increased in breast cancer tissues and cells." (PMID 26918449, 2016). "In this study, we have determined the involvement of MALAT1 in different subtypes of breast cancer." (PMID 27250026, 2016). "MALAT1 can induce breast cancer cell migration and invasion by sponging miR-1." (PMID 27564100, 2016). "MALAT1 was amplified or up-regulated in 7% of breast cancer cases." (PMID 27191888, 2016). "However, the miR-124 mimic revised the overexpression of MALAT1-induced proliferation in breast cancer cells." (PMID 26918449, 2016). "Furthermore, MALAT1 reversed the inhibitory effect of miR-124 on breast cancer proliferation and was involved in the cyclin-dependent kinase 4 (CDK4) expression." (PMID 27191888, 2016). "Lastly, we verified MALAT1's prognostic value in breast cancer." (PMID 27191888, 2016). "To investigate the contribution of MALAT1 in cancer progression in different breast cancer (BC) subtypes, we determined MALAT1 levels in various BC subtype samples using the Cancer Genome Atlas (TCGA) microarray data set, containing 492 BC patient samples of various subtypes." (PMID 27250026, 2016). "Down-regulation of MALAT1 in vitro in cell lines of different cancer types (i.e., breast cancer, colorectal cancer, esophageal squamous cell carcinoma, renal cell carcinoma, and others) leads to reduced cell proliferation by cell cycle arrest at the G2/M phase, and to cell apoptosis." (PMID 26516918, 2015).
breast cancer (continued). "For example, depletion of MALAT1 in CaSki human cervical cancer cells induced G1 arrest and reduced cell growth, cell proliferation, and tumor size, and depletion of MALAT1 in the breast cancer cell line MB231 decreased cell proliferation and triggered G1 arrest." (PMID 25543668, 2014). "In breast cancer, MALAT1 is also upregulated, although its function remains to be determined." (PMID 25400658, 2014). "Though Metastasis associated lung adenocarcinoma transcript 1 (MALAT-1) is first found abnormal expressed in metastasizing non-small-cell lung carcinomas, it is up-regulated in hepatocarcinoma, breast cancer, pancreatic cancer, colorectal cancer, and prostate cancer." (PMID 24063685, 2013). "In conclusion, our study underscores the critical role of MALAT1 in tamoxifen resistance and provides strong evidence that NanoCurcumin can serve as an effective modulator of MALAT1 expression, potentially reversing or preventing endocrine therapy resistance in ER+ breast cancer." (PMID 41031251, 2025). "However, there are additional emerging lncRNAs that have been described as potential biomarkers in cancer, such as HOTAIR, DSCAM-AS1, and GATA3-AS1 in breast cancer, MALAT1 in lung cancer, H19 in colorectal cancer, HULC in liver cancer, UCA1 in bladder cancer, and DLEU1 in endometrial cancer." (PMID 37108589, 2023). "However, other studies reported a decrease in the expression of TUG1 by metformin in vascular wall cells, a decrease in the expression of HOTAIR by metformin in MDA-MB-231 breast cancer cells, and a decrease in the expression of MALAT1 by metformin in cervical cancer cells." (PMID 38053839, 2023). "Similarly, in a 3D breast cancer organoid model, Malat1 ASOs inhibited branching morphogenesis." (PMID 37370745, 2023). "Upregulation of MALAT1 negatively impacts prognosis in different types of cancers, including pancreatic cancer, hepatocellular carcinoma, nasopharyngeal carcinoma, colorectal cancer, breast cancer, osteosarcoma, gastric cancer (GC), lung cancer and esophageal squamous cell carcinoma (ESCC)." (PMID 38203269, 2023). "Consequently, these drugs may inhibit the proliferation of colon and breast cancer cells by modulating the MALAT1–miR-101-3p/miR-129-5p axis." (PMID 37190145, 2023). "However, MALAT1 overexpression inhibited breast cancer metastasis in a mouse model." (PMID 35740618, 2022). "Therefore, MALAT1 may act as a promising therapeutic target for breast cancer metastasis via the PI3K-Akt pathway." (PMID 36685962, 2022). "Therefore, we explored whether MALAT1 can regulate the functions of breast cancer cells through miRNAs." (PMID 34012919, 2021). "Interestingly, most previous studies indicated that the G allele of rs619586 could significantly decrease MALAT1 expression in different cancer types such as DTC, breast cancer, and papillary thyroid cancer (PTC)." (PMID 34268119, 2021). "However, the regulatory mechanism and functions of MALAT1 in breast cancer are still unclear." (PMID 34012919, 2021). "However, the downstream genes of MALAT1/miRNA-3064-5p that influence the functions of breast cancer cells are still unknown." (PMID 34012919, 2021). "Importantly, the general role of MALAT1 acting as a common oncogene and driver of metastasis across multiple cancer types is currently debated and genetic studies in breast cancer indicated that it could also act as a tumour suppressor." (PMID 32727085, 2020). "MALAT1 could serve as a predicting and prognosis marker for breast cancer progression." (PMID 32708561, 2020). "Conversely, MALAT1 may act as a suppressor of breast cancer metastasis." (PMID 32244924, 2020). "Likewise, mutations in Malat1, similar to the SINE deletion, may promote breast cancer resistance by activating the unfolded protein response adaptation pathway." (PMID 31863590, 2020). "Importantly, it has also been reported that MALAT1 is a suppressor of breast cancer metastasis." (PMID 33375322, 2020).
breast cancer (continued). "Moreover, in several studies, MALAT1 down-regulation resulted in a significant decrease of cancer cell migration, whereas in a recent study, MALAT1 suppressed the metastatic ability of breast cancer cells." (PMID 32369931, 2020). "MALAT1 via miR-124/CDK4/E2F1 axis could enhance breast cancer progression." (PMID 33330110, 2020). "We show in this study that the knockdown of MALAT1 reduced the number of invaded cells induced by exogenous Wnt3 protein in HER2+ breast cancer cells, which suggests that MALAT1 may also interact with Wnt3 to induce cell invasiveness and decrease trastuzumab sensitivity in HER2+ breast cancer cells." (PMID 32708561, 2020). "Therefore, MALAT1 regulated the miR-204/ZEB2 axis in breast cancer." (PMID 31214490, 2019). "However, current understanding of the involvement of MALAT1 in breast cancer development and prognosis remains unclear." (PMID 30683807, 2019). "Moreover, knockdown of Malat1 results in mammary tumor differentiation." (PMID 31744046, 2019). "High expression of MALAT1 might predict poor prognosis in breast cancer." (PMID 30683807, 2019). "In addition, recurrent amplification-specific genetic features were identified, including genetic variants in the HIST1H1E and UQCRHL genes and fusion transcripts containing MALAT1 non-coding RNA, which is known to be a prognostic indicator for breast cancer and stimulated by estrogen." (PMID 29844878, 2018). "One recent study observed that knockdown of Malat1 could enhance migration and invasion in breast cancer cells, while a subsequent study reported the opposite outcome, specifically, Malat1 overexpression could induce migration and invasion in breast cancer cells." (PMID 29912916, 2018). "Therefore, MALAT1 upregulation and miR-124 down-regulation is a frequent event in breast cancer tissues and breast cancer cells, and may be involved in malignant tumor development." (PMID 26918449, 2016). "Moreover, we observed a link between MALAT1 mRNA overexpression and HR-positive tumours (a marker of good prognostic), suggesting that MALAT1 could be an ER-induced gene in breast cancer." (PMID 27172249, 2016). "Compared with other breast cancer types, the highly metastatic MDA-MB-231 cells concurrently exhibited increased expression levels of Lysine-specific demethylase 5B protein (KDM5B) and long non-coding RNA (lncRNA), MALAT1, suggesting their functional association." (PMID 26917489, 2016). "Most breast cancer cells (clusters 0–5) exhibited high levels of hypoxia‐related genes, including HSPA1A, MT2A, S100A11, MALAT1, and UBC." (PMID 39805002, 2025). "Recent research has elegantly demonstrated this by showing that microRNA-1 (miR-1) suppresses breast cancer progression by downregulating the oncogene K-RAS and the long lncRNA MALAT1." (PMID 41011238, 2025). "Hormone receptors: In breast cancer, SOX2 and MALAT1 were upregulated in ER/PR-negative and HER2-positive cases, reflecting their association with more aggressive phenotypes." (PMID 40674376, 2025). "In glioblastoma, lncRNAs like MALAT1 and HOTAIR contribute to tumor growth and resistance through similar immunosuppressive mechanisms within the tumor microenvironments seen in breast cancer." (PMID 41031251, 2025). "The expression levels of long non-coding RNAs (lncRNAs) HOTAIR, MALAT1, and UCA1, as well as cancer stem cell-related genes FOX, SNAIL, and ZEB, were analyzed in metastatic breast cancer stem cells (MBCSCs) compared to a healthy control group." (PMID 40781106, 2025). "MALAT1, UCA1, CYTOR, HOTAIR, and GAS5 expressions were compared between breast cancer patients treated with tamoxifen alone (control) and those treated with tamoxifen plus NanoCurcumin (target group)." (PMID 41031251, 2025). "In breast cancer, SOX2 and MALAT1 expression were significantly elevated in ER/PR-negative and human epidermal growth factor receptor 2 (HER2)-positive cases, cancers that are associated with poor prognosis and high metastatic potential." (PMID 40674376, 2025).
breast cancer (continued). "Research has identified several lincRNAs, such as MALAT1, NKILA, and ANCR, that inhibit breast cancer metastasis, in contrast to lincRNAs known to promote it." (PMID 39997609, 2025). "Bioinformatic analysis of publicly available breast cancer datasets of protein–DNA and ncRNA–DNA binding interactions has identified 1293 genomics regions shared by PRC2 and MALAT1." (PMID 38674413, 2024). "To assess the functionality of the MALAT1/NR4A1 axis, we transfected MCF7 breast cancer and PANC1 pancreatic adenocarcinoma cells with Gapmers to downregulate MALAT1 expression." (PMID 38791553, 2024). "An example of a pair with strong correlation is the lncRNA MALAT1, a key regulator in breast cancer, and the mRNA MATR3, an RNA-binding protein with tumor suppressive function in breast cancer." (PMID 38838009, 2024). "This work suggests a tailored immunotherapeutic strategy to regulate TAM-mediated immune reactions in breast cancer subtypes by epigenetically adjusting the expression of CD80 and MSLN by modifying MALAT-1 and HOTAIR." (PMID 38511067, 2024). "We also expanded our analysis to include breast cancer cell lines with varied A3B expression and minimal A3A interference, and quantified C > U editing of DVRs within NEAT1 and MALAT1, the two transcripts with highest degree of C > U editing, using ddPCR." (PMID 39322638, 2024). "The lncRNAs MALAT1 and XIST are two important cancer-related molecules previously studied in several breast cancer contexts." (PMID 37835376, 2023). "Using public genome-binding datasets for PRC2 and MALAT1 derived from independent ChIP- and CHART-seq experiments performed with the breast cancer cell line MCF7, we searched for regions containing PRC2 and MALAT1 overlapping peaks." (PMID 37367050, 2023). "For example, PCA3 (prostate cancer antigen 3, lncRNA) is considered a biomarker in prostate cancer, and the high expression of lncRNAs CCAT2, MALAT1, and NEAT1 is related to worse OS in breast cancer." (PMID 36924407, 2023). "Previous reports on breast cancer have demonstrated that TALAM1 contributes to the stability of MALAT1, promoting the 3′ cleavage and maturation of MALAT1 and decreasing the migration and invasion of cancer cells." (PMID 37754231, 2023). "We present here an in silico study to identify genomic regions co-occupied by the lncRNA MALAT1 and the repressive epigenetic complex PRC2 in the MCF7 breast cancer cell line." (PMID 37367050, 2023). "For instance, lncRNA MALAT1 interacted with the promoter regulatory element of eEF1A1 and affected the status of H3K4 methylation in the gene promoter in breast cancer." (PMID 35607944, 2023). "Fibro_5 cells were characterized by conserved and nuclear-enriched lncRNA (MALAT1, NEAT1), and MALAT1 modulates the expression of cell cycle-related genes in lung fibroblast and EMT-related genes in breast cancer." (PMID 35935940, 2022). "LncRNAs MALAT1 and LINC00963 contribute to radioresistance in nasopharyngeal cancers and breast cancers, respectively." (PMID 36010595, 2022). "Accumulating studies have shown that lncRNAs such as MALAT1 and ZFAS1 are closely related to breast cancer." (PMID 36530425, 2022). "eNEMAL is transcribed from the MALAT1 enhancer locus, between MALAT1 and NEAT1 loci, and it is upregulated in response to hypoxia in various breast cancer cell lines." (PMID 35454885, 2022). "METTL3 regulated MALAT1/E2F1/AGR2 pathway and subsequently controlled Adriamycin resistance in breast cancer." (PMID 36212476, 2022). "In addition, lncRNA-ATB, metastasis-associated lung adenocarcinoma transcript 1 (MALAT1) and lncRNA H19, which are abnormally expressed in TNBC, may provide a less invasive diagnostic procedure to reveal immunological insight of breast cancer." (PMID 36685907, 2022). "Functionally, MALAT1 overexpression elevates the proliferation rate, EMT process, and metastatic potential of breast cancer cells." (PMID 35842651, 2022).
breast cancer (continued). "Recently, MALAT1 was reported to bind and inactivate TEAD (TEA/ATTS domain), inhibiting breast cancer metastasis in transgenic, xenograft, and syngeneic mouse models." (PMID 35585970, 2022). "MIR29B2CHG, NEAT1, MALAT1, AC005332.4, NORAD, and XIST were elevated in normal breast samples than in breast cancer samples." (PMID 35756601, 2022). "The expression of MALAT1 is upregulated, and MALAT1 can promote the expression of high mobility group A2(HMGA2) by sponge miR-26b, thereby promoting the development of breast cancer." (PMID 35707365, 2022). "For example, MALAT1, HOTAIR, lincRNAp21, GAS5, TUG1, and ncRNA-CCND1 were identified in EVs derived from human cervical and breast carcinomas." (PMID 35250537, 2022). "For example, the interaction between MALAT1 target, miR-143-3p, and RALGAPA2 is affected by a functional SNP rs3827693 in breast cancer." (PMID 34746128, 2021). "The precise implication of PVT1/PAI-1 and MALAT1, NEAT1/OPN/HOTAIR networks in breast cancer development is still unclear." (PMID 33670447, 2021). "Several lncRNAs, such as MALAT1, RAB11B-AS1, TROJAN, and HOST2, have been found to facilitate the proliferation and metastasis of breast cancer cells." (PMID 34446703, 2021). "The results indicate a role for MALAT1 as a sponge for miRNA, which increases the metastatic potential of MCF-7 breast cancer cells." (PMID 34012919, 2021). "In the present study, we also measured the serum expression levels of HOTAIR, MALAT1, and NEAT1 as possible biomarkers of breast cancer." (PMID 33670447, 2021). "Univariate and multivariate logistic regression analyses were carried out to assess the predictive values of PVT1, MALAT1, NEAT1, HOTAIR, PAI-1, and OPN in breast cancer." (PMID 33670447, 2021). "Altogether, we demonstrated that an eRNA transcribed from a MALAT1 enhancer regulates NEAT1 isoform expression, implicating the MALAT1–20 kb enhancer and its transcript eNEMAL in co-regulation of MALAT1 and NEAT1 in response to hypoxia in breast cancer cells." (PMID 34019552, 2021). "MALAT1 interacts with known ERGs, cancer-related genes from CGC, ER-DEGs, and breast cancer-related genes from GAD, which is consistent with the results from the MCF-7 dataset." (PMID 33987091, 2021). "In contrast, the lncRNA MALAT1 has been found to serve as a ceRNA of the cell division cycle 42 (cdc42) 3′UTR, resulting in enhanced migration and invasion of breast cancer cells by binding miR-1 competitively." (PMID 32708601, 2020). "In conclusion, our study indicated that elevated MALAT-1 expression levels are predictive of unfavorable prognosis, not only for OS but also DFS, RFS, and DSS in breast cancer." (PMID 32700729, 2020). "Meanwhile, studies revealed that in contrast to those metastasis-promoting lncRNAs, other lncRNAs, such as MALAT1, NKILA, and ANCR can suppress breast cancer metastasis." (PMID 32929060, 2020). "However, crossing these Malat1 knockouts into genetic backgrounds of breast cancer and atherosclerosis mouse models could in fact reveal in vivo effects of the lncRNA on these ailments, although the two breast cancer studies showed contradictory results in terms of the direction of the effect." (PMID 32290841, 2020). "MALAT1 binds miR-1, miR-124, and miR-448, and acts as a ceRNA to reduce CDC42 and up-regulate CDK4 expression, leading to breast cancer cell cycle progression, cell migration, and invasion." (PMID 32174966, 2020). "By sponging miR-206, MALAT1 up-regulates ANXA2 and KRAS expression in gallbladder cancer cells, and reduces CDC42 and up-regulates CDK4 expression in breast cancer cells." (PMID 32174966, 2020). "The increased level of MALAT1 after induction of MAT in three distinct cell lines (HT1080 fibrosarcoma cells, MDA-MB-231 breast cancer, and BLM melanoma cell lines) was further experimentally verified by RT-qPCR experiments." (PMID 32369931, 2020).